OTX1 (orthodenticle homeobox 1)
Description:
Probably plays a role in the development of the brain and the sense organs. Can bind to the BCD target sequence (BTS): 5'-TCTAATCCC-3'.
Tractability: PROTAC: UniProt records ubiquitination sites on it.
Gene: Protein-coding gene on chromosome 2 (63,050,057 to 63,057,836, forward strand). Ensembl gene ENSG00000115507.
Subcellular location: Nucleus
Subcellular location (Human Protein Atlas): Nucleoplasm
Gene Ontology:
Molecular function: DNA-binding transcription activator activity, RNA polymerase II-specific; protein binding; RNA polymerase II cis-regulatory region sequence-specific DNA binding; sequence-specific double-stranded DNA binding; DNA-binding transcription factor activity, RNA polymerase II-specific; DNA binding; DNA-binding transcription factor activity
Biological process: positive regulation of transcription by RNA polymerase II; midbrain development; regulation of transcription by RNA polymerase II; regulation of DNA-templated transcription
Cellular component: chromatin; nucleus
Genetic constraint (gnomAD): Loss-of-function variants: 7 observed, 25.87 expected, observed/expected ratio (o/e) 0.27, 90% interval 0.15 to 0.51. The upper end of that interval is the gene's LOEUF score, 0.51, which puts it in group 2 of 6, group 1 being the genes least tolerant of losing a copy. Missense variants: 408 observed, 492.83 expected, observed/expected ratio (o/e) 0.83, 90% interval 0.76 to 0.9. Synonymous variants: 212 observed, 222.16 expected, observed/expected ratio (o/e) 0.95, 90% interval 0.85 to 1.07.
Homologues: Orthologues: chimpanzee OTX1 (100% identical), macaque OTX1 (99% identical), pig OTX1 (98% identical), rat Otx1 (98% identical), mouse Otx1 (97% identical), dog OTX1 (97% identical), guinea pig OTX1 (97% identical), rabbit OTX1 (90% identical), tropical clawed frog otx1 (78% identical), zebrafish otx1 (75% identical). Paralogues in human: OTX2 (56% identical), CRX (41% identical), PAX3 (22% identical), PAX7 (22% identical), ARX (21% identical), OTP (21% identical), PITX2 (21% identical), UNCX (21% identical), PITX1 (20% identical), RAX (20% identical), PHOX2A (20% identical), SHOX2 (20% identical), and 38 more.
Diseases named in the same sentence as OTX1 in open-access papers:
OTX1 is named in the same sentence as 72 diseases in open-access papers, as found by Europe PMC text mining. Sharing a sentence is not in itself a finding about the gene and the disease. The quoted sentences say what the papers report.
breast cancer (10 papers, 2019 to 2024). A primary or metastatic malignant neoplasm involving the breast. "As previously reported, OTX1 was hypermethylated in cancers such as lung, squamous cell carcinomas and breast cancer." (PMID 37779184, 2023). "OTX1 is related to breast cancer, medulloblastomas, colorectal cancer, hepatocellular carcinoma and bladder cancer." (PMID 35565241, 2022). "MIR100HG silencing upregulates miR-5590-3p and downregulates OTX1, resulting in the decrease in cell viability and invasion in breast cancer." (PMID 34381502, 2021). "Recently, OTX1 was found to be over expressed in various cancers, covering breast blastoma, breast cancer, colorectal cancer and hepatocellular carcinoma." (PMID 34559577, 2021). "It has been reported that overexpression and tumor-promoting effects of OTX1 are observed in hepatocellular carcinoma, colorectal cancer, and breast cancer." (PMID 32838760, 2020). "It is therefore unclear whether the prognostic relevance of OTX1 in human mammary carcinoma patients stems from its expression in stromal or cancer cells." (PMID 31505876, 2019). "In particular, miR-3196, which negatively regulates OTX1, is “sponged” by ADPGK-AS1 lncRNA, whose overexpression in breast cancer is a potential prognostic factor." (PMID 38069286, 2023). "OTX1 was also reported to be negatively regulated by miR-3196 and lncRNA ADPGK-AS1 in breast cancer." (PMID 32549762, 2020).
bladder cancer (9 papers, 2018 to 2025). "OTX1 was overexpressed in bladder cancer tissues and cell lines, which was significantly associated with a poor prognosis of bladder cancer." (PMID 37627900, 2023). "For example, one research detects the DNA methylation status of TWIST1, ONECUT2 (2 loci) and OTX1 in urine to diagnose bladder cancer among hematuria patients." (PMID 40855090, 2025). "In this study, we initially utilized the TCGA bladder cancer cohort to investigate potential DNA methylation markers associated with BCa in the ZNF671, OTX1, and IRF8 genes." (PMID 38472940, 2024). "A recent study showed that a hypermethylation site located in the 3′UTR of OTX1 has been utilized for detecting bladder cancer from urine sediments." (PMID 38472940, 2024). "There are more controversies surrounding OTX1 involvement in bladder cancer, which includes several types of cancer arising from bladder and upper urinary tissues and arises when bladder epithelial cells become malignant." (PMID 38069286, 2023). "OTX1 silencing significantly reduced cell viability and inhibited cell proliferation in bladder cancer." (PMID 37627900, 2023). "A genome-wide methylation analysis on bladder cancer and healthy bladder tissues identified, among others, OTX1 as a tumor-specific highly methylated gene." (PMID 38069286, 2023). "More recently, a combination of methylation status of TWIST, ONECUT2, and OTX1 with mutational analyses of FGFR3, TERT, and HRAS has been reported to detect bladder cancer with a sensitivity of 97% and a specificity of 83%." (PMID 29907142, 2018). "However, a more recent study on bladder cancer and healthy tissues and cell lines detected the overexpression of OTX1 in cancer that correlates with poor prognosis in patients." (PMID 38069286, 2023). "Hence, OTX1 may promote bladder cancer progression and might be a potential prognostic biomarker for bladder cancer." (PMID 37627900, 2023). "A combination of five methylation markers (ONECUT2, MEIS1, OSR1, OTX1, and SIM2) resulted in a bladder cancer prediction model, with a sensitivity of 85% and a specificity of 87%." (PMID 37627900, 2023).
colorectal cancer (9 papers, 2015 to 2024). A primary or metastatic malignant neoplasm that affects the colon or rectum. "In addition, orthodenticle homeobox 1 (OTX1) was upregulated and associated with high stage of colorectal cancer." (PMID 29988590, 2018). "Five hypermethylated genes including ZNF471, SND1, SPOCK1, FBLIM1, and OTX1 were detected and confirmed in 68 cases of colorectal cancer, 31 cases of adenoma, and 49 cases of normal control group." (PMID 37779184, 2023). "The methylation degree of ZNF471 was more than 2.9-fold, SND1 was more than 14.5-fold, SPOCK1 was more than 5.8-fold, FBLIM1 was more than 11.1-fold, and OTX1 was more than 6.9-fold in colorectal cancer or colorectal adenoma to that in the normal control." (PMID 37779184, 2023). "Hypermethylated genes of ZNF471, SND1, SPOCK1, FBLIM1, and OTX1 were obtained from methylation chip detection and further confirm analysis in colorectal cancer and adenoma compared with normal tissue, which may be promising diagnostic markers of colorectal cancer and colorectal adenoma." (PMID 37779184, 2023). "Multiple lines of evidence has expounded that OTX1 acted as a cancer facilitator in numerous malignancies, such as colorectal cancer, gastric cancer, and hepatocellular carcinoma." (PMID 32484209, 2020). "Another study in colorectal cancer demonstrated tumor specific DNA methylation of CpG islands located in 3′ exons was associated with up-regulation of IPF1/PDX1 and OTX1 gene expression." (PMID 25682867, 2015). "Our results indicated that ZNF471, SND1, SPOCK1, FBLIM1, and OTX1 methylation may be useful in diagnosing colorectal cancer and adenoma." (PMID 37779184, 2023). "Interestingly, overexpression of OTX1 sustained human colorectal cancer cell proliferation and invasion in vitro and tumor growth in vivo, suggesting a pathogenic role for this homeoprotein in colon cancer." (PMID 32095330, 2020). "Hypermethylated genes of ZNF471, SND1, SPOCK1, FBLIM1, and OTX1 were obtained from methylation chip detection and further confirm analysis in colorectal cancer and adenoma compared with normal tissue, which may be promising diagnostic markers of CRC and colorectal adenoma." (PMID 37779184, 2023). "Furthermore, OTX1 is involved in the epithelial damage promoting colorectal cancer progression." (PMID 32095330, 2020).
hepatocellular carcinoma (8 papers, 2020 to 2024). A malignant tumor that arises from hepatocytes. "For instance, research conducted on hepatocellular carcinoma has shown that an elevated OTX1 expression is associated with a poor prognosis and tumor progression." (PMID 37780815, 2023). "OTX1 further contributes to Hepatocellular carcinoma (HCC) progression by regulating the ERK/MAPK pathway." (PMID 38069286, 2023). "In addition, OTX1 has recently been shown to be involved in the carcinogenesis of colorectal, bladder and hepatocellular cancer." (PMID 33088216, 2020).
pancreatic cancer (6 papers, 2020 to 2024). "Moreover, in pancreatic cancer, targeting OTX1 has been associated with reduced tumor growth and metastasis." (PMID 37780815, 2023). "OTX1 is a downstream target of miR-4516, which is down-regulated in pancreatic cancer tissues and cell lines, suggesting its role as a tumor suppressor." (PMID 38069286, 2023). "Studies revealed that OTX1 is highly expressed in pancreatic cancer tissues and cell lines, and that it interacts with multiple factors in PC." (PMID 38069286, 2023). "MiR-4269, modulating ZEB1/OTX1 axis, exerts tumor inhibitory effects on pancreatic cancer progression and offers a new insight into the clinical treatment of pancreatic cancer patients." (PMID 38069286, 2023). "Its overexpression inhibited pancreatic cancer cell proliferation, migration, and invasion, via negatively regulating OTX1, pointing toward miR-4516/OTX1 interaction as a novel therapeutic target for PC." (PMID 38069286, 2023). "In this study, we demonstrated that miR-4516 was downregulated in pancreatic cancer and cell lines while OTX1 was highly expressed in pancreatic cancer and cell lines." (PMID 32549762, 2020). "Knockdown of OTX1 expression suppressed pancreatic cancer cell migration and invasion, with down-regulated MMP2 and MMP9 expression." (PMID 32549762, 2020). "Overexpression of miR-4516 inhibits pancreatic cancer cell proliferation, migration, and invasion and promotes cell apoptosis via negatively regulating OTX1." (PMID 32549762, 2020). "We demonstrated that overexpression of miR-4516 inhibited pancreatic cancer cell proliferation, migration and invasion, while promoted cell apoptosis via negatively regulating OTX1." (PMID 32549762, 2020). "Consistently, pancreatic cancer cell lines had significantly higher level of OTX1 than that in control cell line HPDE6-C7." (PMID 32549762, 2020). "Overexpression of miR-4516 suppressed pancreatic cancer cell proliferation, migration and invasion, while promoted cell apoptosis via regulating OTX1." (PMID 32549762, 2020). "Combined bioinformatics analysis predicts OTX1 is the downstream target of miR-4516 in pancreatic cancer." (PMID 32549762, 2020). "Consistently, OTX1 was highly expressed in pancreatic cancer tissues and cell lines." (PMID 32549762, 2020). "Together, we demonstrate that miR-4516/OTX1 axis might be a novel therapeutic target for pancreatic cancer treatment." (PMID 32549762, 2020). "We further explored the expression pattern and function of OTX1 in pancreatic cancer." (PMID 32549762, 2020). "Moreover, we demonstrated that miR-4516 regulated pancreatic cancer cell growth, migration, invasion and apoptosis via targeting OTX1." (PMID 32549762, 2020). "Moreover, we found that OTX1 was highly expressed in pancreatic tumor tissues, as demonstrated by immunohistochemical staining." (PMID 32549762, 2020). "Therefore, miR-4516/OTX1 might serve as a novel therapeutic target for miRNA-based therapy in pancreatic cancer." (PMID 32549762, 2020). "MiR-4516 negatively regulates orthodenticle homeobox 1 (OTX1) by binding to its 3’-UTR, resulting in reduction of migration and invasion in pancreatic cancer cells." (PMID 35771766, 2022). "Moreover, miR-4269 overexpression inhibits pancreatic cancer cell proliferation, migration, and invasion by affecting the E-box binding homeobox 1 (ZEB1)/OTX1 pathway." (PMID 38069286, 2023). "Pancreatic tumor tissues also had notably lower levels of OTX1 mRNA compared with that in adjacent non-tumor tissues." (PMID 32549762, 2020). "The function mechanism of OTX1 in pancreatic cancer is not clear." (PMID 32549762, 2020). "OTX1 was highly expressed in pancreatic cancer tissues compared with that in non-tumor tissues." (PMID 32549762, 2020).
gastric cancer (5 papers, 2020 to 2023). A primary or metastatic malignant neoplasm involving the stomach. "Knockdown of OTX1 induced cell apoptosis, and attenuated cell migration and invasion of gastric cancer cells." (PMID 32549762, 2020). "High expression of OTX1 is also observed in solid tumors, such as gastric cancer, sinonasal carcinoma, and olfactory neuroblastoma." (PMID 32838760, 2020). "In gastric cancer, an elevated OTX1 expression has been correlated with worse survival." (PMID 37780815, 2023). "Downregulation of OTX1 inhibited cell proliferation, migration and invasion in gastric cancer." (PMID 32549762, 2020). "Gastric cancer (GC) tissues also present a high expression of OTX1 compared with adjacent non-tumor tissues, both at the mRNA and protein levels, with higher levels in GC that develops lymph node metastasis and in patients with lower survival rate." (PMID 38069286, 2023).
lung carcinoma (5 papers, 2017 to 2023). "Similarly, in lung cancer, abnormal OTX1 expression has been associated with enhanced invasion capability of tumor cells, contributing to metastasis." (PMID 37780815, 2023). "In addition, in lung cancer, OTX1 overexpression has been linked to advanced disease stage and reduced survival." (PMID 37780815, 2023). "In lung cancer, OTX1 knockdown has been shown to suppress cell growth and induce apoptosis, highlighting its potential as a therapeutic target." (PMID 37780815, 2023). "However, aberrant expression of OTX1 has been observed in various cancers, such as lung cancer and colorectal cancer." (PMID 37780815, 2023). "Hub genes including LRRK2, BMI1, MNDA (myeloid cell nuclear differentiation antigen), OTX1, FFAR2, and PITX1 play a significant role in lung cancer progression." (PMID 38137330, 2023). "The data indicated that the CCNE1-high, CCNE1-high/EGR1-low, CCNE1-high/SCGB3A1-low and OTX1-high/CCNE1-high phenotypes, which might be involved in lung cancer malignancy, are related to poor prognosis in lung cancer." (PMID 36918558, 2023). "BARHL2, DMRTA2, OTX1 and OTX2 were identified as DNA methylation markers for lung cancer." (PMID 35313869, 2022).
medulloblastoma (5 papers, 2020 to 2024). A malignant, invasive embryonal neoplasm arising from the cerebellum. "The main tumor in which OTX genes have been studied is medulloblastoma (MB), the most common brain tumor in children, with virtually all medulloblastomas expressing OTX1, OTX2, or both genes." (PMID 38069286, 2023). "Several studies reported the hypermethylation of the OTX1 gene promoter region in non-small lung cancer and an altered OTX1 expression in medulloblastoma and other brain tumors." (PMID 35176995, 2022). "Recently, it has been reported that OTX1 is highly expressed in aggressive non-Hodgkin lymphoma, and medulloblastomas." (PMID 32838760, 2020).
laryngeal squamous cell carcinoma (4 papers, 2020 to 2025). A squamous cell carcinoma that arises from the larynx. "They suggested that increasing miR-129-5p levels could be a potential therapeutic strategy for patients with laryngeal squamous cell carcinoma and high OTX1 expression." (PMID 39337467, 2024). "OTX1 plays a role in the development and progression of laryngeal squamous cell carcinoma." (PMID 39337467, 2024). "Similarly, in laryngeal squamous cell carcinoma, targeting OTX1 impairs tumor cell proliferation and tumor growth." (PMID 37780815, 2023). "Previous studies have shown that overexpression of the OTX1 gene is associated with the progression of various cancers, including glioma, ovarian cancer, cervical cancer, laryngeal squamous cell carcinoma, and esophageal squamous cell carcinoma, suggesting that OTX1 may be an oncogenic driver." (PMID 40711007, 2025). "However, the function of OTX1 in laryngeal squamous cell carcinoma (LSCC) is largely unknown." (PMID 32838760, 2020).
colon cancer (3 papers, 2020 to 2023). "Similarly, OTX1 interacts with lncRNA HNF1A-AS1 and PBX3 in colon cancer to activate the extracellular-signal-regulated kinase/mitogen-activated protein kinase (ERK/MAPK) pathway and promote angiogenesis via the PBX-OTX1-VEGF axis." (PMID 38069286, 2023). "Therefore, OTX1 control of EMT and other pathways could be a potential target for the therapy of colon cancer." (PMID 38069286, 2023).
epilepsy (3 papers, 2014 to 2021). A brain disorder characterized by episodes of abnormally increased neuronal discharge resulting in transient episodes of sensory or motor neurological dysfunction, or psychic dysfunction. "As this was a preliminary study, additional studies should be performed that look at the whole gene sequence in a larger cohort of patients with different ethnicities to clarify the genetic association between OTX1 polymorphisms and epilepsy." (PMID 32211441, 2020). "The main objective of this study was to assess the polymorphisms of the OTX1 coding sequences in a cohort of patients from China based on the hypothesis that these polymorphisms are potentially predictive of epilepsy." (PMID 32211441, 2020). "Previous basic studies considered that OTX1 played a crucial role in the development and evolution of the brain, having a protective effect on epilepsy." (PMID 32211441, 2020). "Symmetrically, Otx2 rescues epilepsy and corticogenesis abnormalities in Otx1 knockout mice but fails to recover the lateral semicircular canal of the inner ear." (PMID 24558479, 2014). "Mice lacking Otx1 develop epilepsy and abnormalities in many brain regions." (PMID 33441551, 2021).
esophageal squamous cell carcinoma (3 papers, 2023 to 2025). Esophageal squamous cell carcinoma (ESCC) is a type of esophageal carcinoma (EC) that can affect any part of the esophagus, but is usually located in the upper or middle third. "In esophageal squamous cell carcinoma, overexpressing OTX1 has been shown to promote tumor growth as well as invasion in nude mice." (PMID 37780815, 2023). "The study showed that OTX1 expression level is an individual prognostic factor for esophageal squamous cell carcinoma (ESCC) patients when OTX is overexpressed in ESCC tissues compared to normal tissues." (PMID 38925618, 2024).
olfactory neuroblastoma (3 papers, 2020 to 2024). An olfactory neuroblastoma arising in the paranasal sinus. "In addition, OTX1 and OTX2 have been identified as two possible molecular markers for sinonasal carcinomas and olfactory neuroblastomas, whereas BACH2 is associated with the neuronal differentiation of N1E-115 neuroblastoma cells." (PMID 32391054, 2020). "Interestingly, only OTX‐1 was identified in non‐intestinal type adenocarcinomas, while OTX‐2 was selectively expressed only in olfactory neuroblastomas." (PMID 38925618, 2024).